LARGE2 (LARGE xylosyl- and glucuronyltransferase 2)
Description:
Bifunctional glycosyltransferase with both alpha-1,3-xylosyltransferase and beta-1,3-glucuronyltransferase activities involved in the maturation of alpha-dystroglycan (DAG1) by glycosylation leading to DAG1 binding to laminin G-like domain-containing extracellular proteins with high affinity and in a phosphorylated-O-mannosyl trisaccharide dependent manner. Elongates the glucuronyl-beta-1,4-xylose-beta disaccharide primer structure by adding repeating units [-3-Xylose-alpha-1,3-GlcA-beta-1-] to produce a heteropolysaccharide (By similarity). Supports the maturation of DAG1 more effectively than LARGE1. In addition, can modify both heparan sulfate (HS)- and chondroitin/dermatan sulfate (CS/DS)- proteoglycans (PGs), namely GPC4, with a glycosaminoglycan (GAG)-like polysaccharide composed of xylose and glucuronic acid to confer laminin binding (By similarity).
Synonyms: GYLTL1B; PP5656; FLJ35207
Tractability: Antibody: UniProt predicts a signal peptide or a membrane-spanning region.
Gene: Protein-coding gene on chromosome 11 (45,918,146 to 45,929,376, forward strand). Ensembl gene ENSG00000165905.
Subcellular location: Golgi apparatus membrane
Pathways (Reactome):
Metabolism of proteins: Matriglycan biosynthesis on DAG1
Gene Ontology:
Molecular function: protein binding; glucuronosyltransferase activity; manganese ion binding; UDP-xylosyltransferase activity; xylosyltransferase activity; dystroglycan binding; glycosyltransferase activity
Biological process: protein O-linked glycosylation via mannose; muscle cell cellular homeostasis; protein O-linked glycosylation
Cellular component: Golgi membrane; Golgi apparatus
Genetic constraint (gnomAD): Loss-of-function variants: 67 observed, 72.51 expected, observed/expected ratio (o/e) 0.92, 90% interval 0.76 to 1.13. The upper end of that interval is the gene's LOEUF score, 1.13, which puts it in group 4 of 6, group 1 being the genes least tolerant of losing a copy. Missense variants: 925 observed, 920.22 expected, observed/expected ratio (o/e) 1.01, 90% interval 0.95 to 1.06. Synonymous variants: 428 observed, 394.35 expected, observed/expected ratio (o/e) 1.09, 90% interval 1 to 1.18.
Homologues: Orthologues: chimpanzee LARGE2 (99% identical), rabbit LARGE2 (88% identical), pig LARGE2 (87% identical), dog LARGE2 (86% identical), rat Large2 (83% identical), guinea pig LARGE2 (83% identical), mouse Large2 (82% identical), tropical clawed frog large2 (66% identical), macaque LARGE2 (65% identical), zebrafish large2 (65% identical), Caenorhabditis elegans lge-1 (30% identical), Drosophila melanogaster CG11149 (12% identical), and 10 more. Paralogues in human: LARGE1 (64% identical), B4GAT1 (14% identical), GXYLT1 (12% identical), GXYLT2 (12% identical), XXYLT1 (11% identical).
Diseases named in the same sentence as LARGE2 in open-access papers:
LARGE2 is named in the same sentence as 16 diseases in open-access papers, as found by Europe PMC text mining. Sharing a sentence is not in itself a finding about the gene and the disease. The quoted sentences say what the papers report.
prostate carcinoma (4 papers, 2015 to 2022). A carcinoma that arises from epithelial cells of the prostate gland. "Indeed several studies have identified reduced expression of individual enzymes including LARGE, LARGE2 and β3GNT1 in breast and prostate cancer associated with hypoglycosylation of αDG." (PMID 26220087, 2015). "Further, LARGE2 expression inversely correlated with tumor progression, from a localized to an invasive stage, in a tissue cDNA microarray organized according to prostate cancer stage." (PMID 36494657, 2022). "Decreased expression of LARGE2 (by ‒ 3.15-fold) has also been reported in prostate cancer." (PMID 36494657, 2022). "Finally, decreased mRNA levels of the LARGE2 gene have been detected in the PANC-1 and BxPC-3 cell lines of pancreatic cancer, TEM4-18 of prostate cancer, A498 of renal cell carcinoma, and MDA-MB-231 and ZR-75-1 of breast cancer, whereas in colon cancer cell lines they were highly variable." (PMID 36494657, 2022).
dystroglycanopathy (2 papers, 2010 to 2020). "This indicates that data obtained from α-dystroglycanopathy hiPSCs with LARGE mutations should be interpreted with caution, because LARGE2 enzymatic activity could be rescuing functional glycosylation of αDG." (PMID 32423971, 2020). "Overexpression of LARGE (or LARGE2) by means of genetic or pharmacological intervention could restore ligand binding and improve muscle strength in patients affected by dystroglycanopathies." (PMID 21203384, 2010). "This has led to the suggestion that the administration of pharmacologically active small molecules, capable of upregulating LARGE, or LARGE2 which however is essentially not expressed in muscle, or both, could be an interesting therapeutic strategy for a broad range of dystroglycanopathy patients." (PMID 21203384, 2010).
adenoma (1 paper, 2020). A neoplasm arising from the epithelium. "According to public microarray data derived from 32 patient-matched human colonic mucosa-adenoma pairs (GSE8671), LARGE2 levels were slightly elevated in human adenoma specimen." (PMID 32586342, 2020). "ISH against Large2 on FFPE sections derived from ApcMin mice revealed elevated abundance of Large2 mRNA in adenoma, which also showed membranous O-glycosylated α-DG as visualized by IHC staining." (PMID 32586342, 2020). "During CRC-initiation, the length and hence the functionality of truncated APC, which translates to different doses of oncogenic Wnt activity, influences the level of LARGE2 expression and the O-glycosylation status of α-DG in human adenoma organoids." (PMID 32586342, 2020). "In human adenoma organoids, activity of the LARGE2/α-DG axis was Wnt-dose dependent." (PMID 32586342, 2020).
colon cancer (1 paper, 2020). "Considering a well-accepted segregation of colon cancer into four distinct sub-groups known as the consensus molecular subtypes (CMS), we wondered if expression of LARGE2 was associated with one of these categories." (PMID 32586342, 2020). "In CRC, the expression of LARGE2 correlates with Wnt signaling intensity, an intestinal stem cell phenotype, and expression of human colonic epithelial stem cell genes in different cohorts of colon cancer patients." (PMID 32586342, 2020). "Next, we used NGS RNA-Seq data derived from 458 colon cancer and 167 rectal tumors from TCGA as provided by the NCI-GDC, and we generated pre-ranked lists of genes according to their Pearson correlation with LARGE2 gene expression (data not shown)." (PMID 32586342, 2020).
leukemia (1 paper, 2022). A malignant (clonal) hematologic disorder, involving hematopoietic stem cells and characterized by the presence of primitive or atypical myeloid or lymphoid cells in the bone marrow and the blood. "Furthemore, in solid tumors and derived cell lines (i.e., leaving aside leukemia) genes directly involved in the synthesis of core M3 glycan and matriglycan, such as POMGNT2, CRPPA, B4GAT1, LARGE1 and LARGE2 and/or their encoded proteins, are found downregulated." (PMID 36494657, 2022).
renal carcinoma (1 paper, 2020). A carcinoma arising from the epithelium of the renal parenchyma or the renal pelvis. "While Wnt-driven CRC cells showed enhanced LARGE2 expression, matriglycan-complexity on α-DG, and affinity towards laminin, studies on prostate and renal cancer provided evidence that O-glycosylated α-DG interferes with cellular migration and invasiveness." (PMID 32586342, 2020).
cancer (5 papers, 2013 to 2022). A tumor composed of atypical neoplastic, often pleomorphic cells that invade other tissues. "Recently, two other dystroglycan-modifying glycosyltransferases, LARGE2 and B4GALNT2, were linked with the cancer-associated abnormal glycosylation of α-dystroglycan." (PMID 31054580, 2019). "The silencing of the E-cadherin encoding gene, CDH1, is mediated by the EMT-promoting transcription factors ZEB1 and Snail, two regulators that are overexpressed in many cancers, and which act jointly to repress both CDH1 and LARGE2 mRNAs." (PMID 36494657, 2022). "Unlike other genes that have been implicated in DG hypoglycosylation in cancer, such as B3GnT1, LARGE, and LARGE2; ISPD does not yet have a defined glycosyltransferase enzymatic activity and how it is involved in the process of DG glycosylation is unclear." (PMID 26220087, 2015). "We obtained similar results with a pre-ranked list of LARGE2 correlated genes derived from the CRIS gene expression data set (n = 515 PDX CRC samples) and from microarray data (n = 58 established CRC cell lines) obtained from the Cancer Cell Line Encyclopedia (CCLE)." (PMID 32586342, 2020).
tumor (3 papers, 2015 to 2022). "GYLTL1B, the gene encoding LARGE2, demonstrated the greatest magnitude change with a nearly 80 % reduction in tumor compared to normal." (PMID 26220087, 2015). "This points to Wnt/LARGE2/α-DG signaling as a rather tumor-restrictive mechanism at early invasive disease stages, where CRC cells need to overcome the boundaries of the BM to achieve tumor dissemination." (PMID 32586342, 2020). "Full blown CRC cells and patient-derived tumor organoids show an overall increased but heterogenous occurrence and molecular weight of O-glycosylated α-DG, which at least partially depends on Wnt signaling and LARGE2 functionality." (PMID 32586342, 2020). "Finally, after accounting for these chromosomal alterations, we discovered that LARGE, the homologue of LARGE2, exhibits the next highest level of downregulation with a ~56 % reduction in tumor compared to normal." (PMID 26220087, 2015). "O-glycosylated α-DG represented a Wnt/LARGE2-dependent feature in CRC cell lines and patient-derived tumor organoids." (PMID 32586342, 2020). "We noticed that LARGE2 expression in full-blown CRC and patient-derived PDTOs was strongly elevated when compared to normal tissues and pre-malignant APC-MCR mutant ADOs, which might reflect an upregulation of tumor cell intrinsic Wnt activity during tumor progression." (PMID 32586342, 2020). "To better address if LARGE2 was differentially expressed between non-metastatic (M0) or liver-metastatic (M1) primary CRC tissues, we isolated total RNA from FFPE tumor-enriched areas from M0 (n = 12) or M1 (n = 12) CRC cases." (PMID 32586342, 2020).
LARGE2 also shares sentences with these, for which no sentence is quoted: breast carcinoma (2 papers); colorectal cancer (2); renal cell carcinoma (2); clear cell renal cell carcinoma (1); colorectal tumors (1); metastatic disease (1); ovarian carcinoma (1); rectal tumors (1).